BRCA1 (BRCA1 DNA repair associated)
Diseases named in the same sentence as BRCA1 in open-access papers (continued):
Sharing a sentence is not in itself a finding about the gene and the disease.
tumor (continued). "It is interesting that the BRCA1 and BRCA2 tumours appear to be opposites with respect to their characteristics in the age groups of younger and older patients." (PMID 15987451, 2005). "Second, our finding of 8.6% prevalence of occult tumours is established in BRCA1 mutation carriers undergoing prophylactic salpingo-oophorectomy, while other series did not make a clear distinction between a salpingo-oophorectomy or an oophorectomy, nor between BRCA1 and BRCA2 carriers." (PMID 15083174, 2004). "It is well known that BRCA1 and BRCA2 reach their maximal levels in late G1 and S phases in normal and tumour-derived breast epithelial cells." (PMID 12838319, 2003). "LOH was found in the RAD51 region in 32% of tumours, in the RAD52 region in 16%, in RAD54 in 20% and in the BRCA1 and BRCA2 regions in 49% and 44% respectively." (PMID 10507777, 1999). "Therefore, DREAM- and RB-mediated transcriptional control of BRCA1 and BRCA2 constitutes a critical component of the regulatory network governing DNA repair, cell survival, and tumor suppression." (PMID 40841483, 2026). "Additionally, our findings provide mechanistic insight that supports and extends a previously proposed rationale for why BRCA1 and BRCA2 typically fail to exert tumor-suppressive functions in most cell types." (PMID 40841483, 2026). "The paradigmatic example of BRCA1/2 deficiency and PARP inhibition illustrates how exploiting tumour‐specific DDR defects can achieve selective tumour cell killing without substantially increasing toxicity to normal tissues." (PMID 41537447, 2026). "BRCA1 and BRCA2 are core tumour suppressor genes in the HRR pathway." (PMID 41537447, 2026). "Two patients with BRCA mutations (one somatic BRCA1/2 and one germline BRCA2) showed no tumor response." (PMID 40743286, 2025). "In vivo studies further revealed that 5-formamidoimidazole-4-carboxamide ribotide treatment effectively suppressed tumor growth, with overexpression of METTL1 or BRCA1 reversing the inhibitory effects of 5-formamidoimidazole-4-carboxamide ribotide on tumor growth." (PMID 41430564, 2025). "A notable increase is also observed in the localization of M1 macrophages in BRCA1 mutant samples, with these cells infiltrating into the tumor cells, while no such phenomenon is observed in HRP samples." (PMID 40830526, 2025). "As in the targeted monotherapies, also in the combinatorial setting, routine multi-gene NGS of both tissue and circulating tumor DNA is now the standard of care, with the 2025 NCCN guideline mandating HRR-gene screening (BRCA1/2, ATM, PALB2, etc.)for every mCRPC patient." (PMID 40806607, 2025). "In contrast, as previously shown in this tumor model, BRCA1 fails to load into DNA repair foci after the TCD50 dose of 15 Gy, an event dependent on induction of the ASMase-ceramide–mediated SSR." (PMID 40402574, 2025). "BRCA1 and BRCA2 are two tumour suppressor genes that play a role in DNA repair processes." (PMID 40844552, 2025). "Conversely, the stage of recurrent tumor, histological subtype, locoregional involvement of primary and recurrent tumors, and BRCA1 and BRCA2 status did not significantly affect HER2 conversion." (PMID 40282854, 2025). "Future studies should investigate these potential non-canonical roles to further elucidate BRCA1’s multifaceted contributions to tumour suppression." (PMID 40966517, 2025). "GSK3B-53BP1 axis controls HR-mediated DSB repair and determines synthetic lethality response of tumor cells to PARP1 inhibition independent of BRCA1 status." (PMID 41243969, 2025).
tumor (continued). "Our study uncovered a mechanism underlying the interactions among BRCA1, E2/ERα, and downstream signaling in suppressing PABC and non-PABC tumor formation." (PMID 40157910, 2025). "Current guideline recommendations for germline BRCA1/2 testing are based on tumor phenotype and family history rather than age alone." (PMID 41245818, 2025). "BRCA1 and BRCA2 are two critical tumor suppressor genes crucial for DNA double-strand break repair." (PMID 39987121, 2025). "The primary outcome was the percentage of patients completing the BRCA1/2 test-pathway, defined as having a negative tumor test or a referral for a germline test in case of a positive tumor test or no tumor test." (PMID 40323485, 2025). "This indicates that the contribution of cGAS-STING signaling to the BRCA1/2–PARPi SL is not tumor cell-autonomous (i.e., it relies on non-tumor cell lineages) and is best explained by cGAS-STING signaling activating a T-cell-mediated immune response." (PMID 40730818, 2025). "Notably, BRCA1 partners with BARD1 and additional tumor-suppressor proteins to exert critical functions in DNA repair, replication-fork maintenance, and tumor suppression." (PMID 41463377, 2025). "In 47 out of 100 tested patients with highest methylation level (> 14%) and absent or low BRCA1 expression in tumor tissue (< 10% cells with immunoreactivity), we searched for germline alterations in the BRCA1 promoter region." (PMID 40495194, 2025). "Cord blood from newborns (WBCs) DNA methylation of the ACSL3 promoter, Intragenic p19INK4α DNA methylation in adult blood (PBLs), CDH1, HIN1, PARPβ, and TWIST promoter DNA methylation in adult tumor tissue DNA methylation of the ESR1 promoter, BRCA1, CCND2, and DAPK." (PMID 40182693, 2025). "The administration of the vaginal metabolite 5-formamidoimidazole-4-carboxamide ribotide to HGSOC cells and xenografted tumor models in nude mice resulted in the inhibition of cell proliferation and tumor growth of HGSOC, which was achieved by the inhibition of the METTL1/BRCA1 axis." (PMID 41430564, 2025). "There was a notable divergence in gene expression levels between neoplastic and neighboring tissues, with genes such as BRCA1, CHEK2, and IKBKE substantially amplified in tumor tissues, while genes such as ZMYND11, MAPK8, and RPS3 exhibited notable elevation in adjacent nontumor tissues." (PMID 41497799, 2025). "Deficient HRR, primarily due to BRCA1/BRCA2 mutations, non-BRCA HRR gene alterations, and epigenetic changes, influences tumor behavior and enhances sensitivity to platinum-based chemotherapy and PARPi." (PMID 40864792, 2025). "Since the initiation of this BRCA1/2 testing workflow is tumor- rather than patient-based, this approach is considered more inclusive than germline-based approaches." (PMID 40323485, 2025). "Also in vivo, BBIT20 inhibited HR DNA repair as evidenced by the significant decrease of BRCA1 and RAD51 expression levels in tumour tissues." (PMID 40275348, 2025). "Tumor stage, histological subtype, locoregional involvement of primary and recurrent tumors, BRCA1 and BRAC2 status, and HER2 do not significantly correlate with ER conversion." (PMID 40282854, 2025). "Patients with gBRCA1m, sBRCA1m, or tumor BRCA1-PM did not have significantly different DRFS compared to BRCA1-non-altered patients." (PMID 38191387, 2024). "These samples underwent BRCA1 gene expression analysis and CA15-3 tumor marker assessment." (PMID 39742378, 2024).
tumor (continued). "Among the 399 patients with BRCA1 status, 26.3% had a gBRCA1m, 5.3% had a sBRCA1m, 36.6% had tumor BRCA1-PM, and 31.8% had BRCA1-non-altered tumors." (PMID 38191387, 2024). "Tamoxifen has shown effectiveness in BRCA2 carriers, who often have estrogen receptor-positive tumours, unlike BRCA1 tumours, which typically present as triple-negative." (PMID 39421188, 2024). "We noticed that the number of Brca1+/− or Gata3+/− tumor cells, but not the number of Gata3+/+;Brca1+/+ tumor cells, was significantly reduced after OLA treatment." (PMID 38627785, 2024). "Furthermore, resistance is evident in tumours with heterozygous methylation of BRCA1 whilst homozygosity or hemizygosity is predictive of PARPi response in PDX models and tumour samples." (PMID 39135999, 2024). "In total, 399 patients were classified into four groups: BRCA1-non-alteration (31.8%), gBRCA1m (26.3%), sBRCA1m (5.3%), and tumor BRCA1-PM (36.6%)." (PMID 38191387, 2024). "Since PARPi resistance in the Brca1-def and Bard1-def models was more faithfully recapitulated in-vivo than in vitro (EV1), we hypothesized that signals from the tumor microenvironment are important for mediating PARPi resistance." (PMID 38956205, 2024). "Notably, BRCA1 and BRCA2 stand as tumor-suppressor genes essential to the preservation of genomic integrity through the mending of dsDNA lesions employing homologous recombination (HR)." (PMID 38397209, 2024). "This study provides evidence that BRCA1/2-deficient and/or HRD cell lines comprise a heterogeneous group in which most (i.e., 82.4%) BRCA1/2-deficient cell lines have an HRP phenotype and therefore do not represent HRD tumor specimens." (PMID 38398132, 2024). "Each tumor genome was classified according to their HRD and RB1 status, resulting in six groups: BRCA1-HRD & RB1 altered (n = 13); BRCA1-HRD & RB1 wild-type (n = 36); BRCA2-HRD & RB1 altered (n = 8); BRCA2-HRD & RB1 wild-type (n = 20); HRP & RB1 altered (n = 4); or HRP & RB1 wild-type (n = 45)." (PMID 38837893, 2024). "When the subgroups of women with a germline BRCA1 and BRCA2 PV were analysed separately, there was a trend towards a significantly greater proportion of tumours with CRS3 in the germline BRCA2 PV subgroup compared to the germline BRCA1/2 wild type group (OR 2.13, 95% CI 0.95–4.91; P = 0.0647)." (PMID 39550490, 2024). "Although tumours carrying BRCA1 PVs typically do not express oestrogen receptor alpha (ERα), studies have demonstrated that these cells can still respond to elevated oestrogen levels independently of oestrogen receptor expression." (PMID 39682099, 2024). "In the PROfound trial, a crossover randomized phase III trial, patients with mCRPC with BRCA1, BRCA2, and ATM tumor alterations showed improved survival when treated first-line with olaparib compared to enzalutamide or abiraterone (19.1 months vs. 14.7 months, HR = 0.69; p = 0.02)." (PMID 38927984, 2024). "OLA treatment of sh-Gata3-Brca1+/+;Gata3+/+ tumor cells, not sh-Ctrl-Brca1+/+;Gata3+/+ tumor cells, again significantly reduced the number of colonies formed." (PMID 38627785, 2024). "Strong concordance (97.8%) was observed between tumor BRCA and germline BRCA mutations analyzed by FoundationOne®CDx and BRACAnalysis CDx®, respectively, except for one patient who exhibited a germline BRCA1 mutation but lacked a tumor BRCA mutation." (PMID 38869771, 2024). "BRCA1 and BRCA2 (BRCA) are two of the important tumor suppressor genes." (PMID 38671360, 2024).
tumor (continued). "We previously discovered that Brca1 positively regulates GATA3 expression and that GATA3 functions downstream of BRCA1 suppressing luminal-to-basal and to mesenchymal differentiation in mammary cells as well as tumor development and progression." (PMID 38627785, 2024). "We previously reported that none of the PARPi-resistant BRCA2-deficient tumours restored RAD51 IRIF12, whereas 64% (29/45) of the BRCA1-deficient tumours became RAD51 IRIF+." (PMID 38789420, 2024). "Unlike many other tumor suppressors, BRCA1/BRCA2 inactivation leads to embryonic lethality in mice and inhibits cellular proliferation in human and murine cells in vitro." (PMID 39198848, 2024). "Although BRCA1 promoter methylation has no obvious effect on tumor development per se, it can increase the sensitivity of tumor cells to PARPi." (PMID 39318358, 2024). "It should be noted that the BRCA1/2 tumor test rate of 50.3% reported in this study does not imply that only half of all patients received BRCA1/2 testing." (PMID 38730634, 2024). "We also show that SCAF1 deficiency partly rescues RAD51 loading in cells lacking the BRCA1 tumor suppressor." (PMID 38880245, 2024). "Although the interaction between sTILs and tumor BRCA1-PM was not statistically significant (the final model did not include this interaction term), the direction of the interaction was the same as in the model for OS." (PMID 38191387, 2024). "Our study found that in patients with GC without BRCA1 mutations, the PARP1 inhibitor OLP combined with AIL inhibiting BRCA1, and they work hand in hand to inhibit HR and BER pathways with powerful anti‐tumour effects." (PMID 38009603, 2024). "Every 10% sTIL increment was associated with 16% higher OS (adjusted HR, 0.84; 95% CI, 0.78–0.90) in gBRCA1m, sBRCA1m, or BRCA1-non-altered patients and 31% higher OS in tumor BRCA1-PM patients." (PMID 38191387, 2024). "For instance, in the ARIEL 2 trial, a large deletion of BRCA1 that restored the open reading frame in a platinum-resistant patient was detected in the tumor sample but not in ctDNA." (PMID 38544832, 2024). "However, in the presence of BRCA1 PVs, CAFs reduced the expression of E-cadherin while overexpressing fibronectin, vimentin, and N-cadherin, allowing for easier induction of EMT of tumour cells." (PMID 39682099, 2024). "The analysis revealed a significant downregulation of the BRCA1 gene expression in methylated tumor samples as compared to non-methylated tumors and normal tissues, suggesting the role of epigenetic silencing." (PMID 39246954, 2024). "Yet, when only high-impact variants were considered, BRCA1 (but not BRCA2) was, as expected, more frequently altered in hgOvCa in comparison with all the remaining tumor groups." (PMID 39456660, 2024). "Patients with a sBRCA1m or tumor BRCA1-PM did not have significantly different OS compared to BRCA1-non-altered patients." (PMID 38191387, 2024). "We found a lower incidence of second primary tumors in tumor BRCA1-PM patients, compared to BRCA1-non-altered patients." (PMID 38191387, 2024). "Taken together, the overexpression of BRCA1 is an independent risk factor for LUAD rather than LUSC, and is indicative of an immune‐suppressive tumor microenvironment." (PMID 38090061, 2023). "Whereas depletion of either CD8+ or CD4+ T cells alone did not affect treatment efficacy of olaparib and AZD1775 suggesting that the cytotoxicity of both CD8+ and CD4+ T cells is essential for the anti-tumour efficacy of combined PARP and WEE1 inhibition in the BRCA1/2 wild-type AT3OVA TNBC model." (PMID 37582853, 2023). "Following SEALigHTS validation for BRCA1 and BRCA2, our hypothesis was tested using an independent research set of 95 pairs from tumor and adjacent normal breast tissues." (PMID 37046838, 2023).
tumor (continued). "To conclude, the BRCA1 c.-107A > T SNV is not prevalent in a large cohort of patients with tumor BRCA1 promoter hypermethylation." (PMID 36112334, 2023). "B7-H3 is overexpressed in tumours with defective DNA repair (DDR) gene (ATM, BRCA1/2) alterations compared to tumours without DDR gene alteration." (PMID 36114082, 2023). "For instance, studies have revealed that tumor cells lacking BRCA1 or BRCA2 genes exhibit sensitivity to PARP inhibitors, suggesting a potential treatment option for patients with these mutations." (PMID 37781203, 2023). "None of the patients with two primary tumors revealed either tumor or WBC BRCA1 methylation, and none of these tumors were either TNBC or ER low expressing tumors." (PMID 38053165, 2023). "While one patient with a somatic BRCA1 PV harbored tumor tissue BRCA1 methylation in concert, no BRCA1 methylation was detected in this patient’s WBCs, indicating the tumor BRCA1 methylation, similar to the PV, to be a somatic event." (PMID 38053165, 2023). "Our data suggest that tumour BRCA1/2 and HRD testing is adequate for patients diagnosed with non-mucinous high-grade EOC aged ≥80, with germline BRCA1/2 testing reserved for women with a tumour BRCA1/2 PV/LPVs." (PMID 36765687, 2023). "In all the cases, TAZ transcriptional activity was raised upon BRCA1 silencing, thus supporting the hypothesis of a general regulation of TAZ by BRCA1, both in normal and in tumor cells." (PMID 37887275, 2023). "To further investigate potential perturbation of HRD genes, we also investigated BRCA1 methylation levels in the cohort and did not identify any tumour with hyper-methylation of the promoter region of the BRCA1 gene." (PMID 37258531, 2023). "Inhibitors of PARP1/2 (PARPi) became of interest due to synthetic lethality wherein tumor cells lacking BRCA1/2 function are especially sensitive to PARPi, leading to specifically targeted tumor cell death." (PMID 37844763, 2023). "The tumor stage (T) classification was predominantly T2 for BRCA1 carriers and noncarriers, while for BRCA2 carriers, T2 and T3 were more common (p = 0.260)." (PMID 37485802, 2023). "Notably, among these 17 patients, 10 (58.9%; CI 32.9–81.6%) also carried WBC BRCA1 methylation (WBC and tumor tissue methylation concordance: P < 0.001)." (PMID 38053165, 2023). "Anti-PD-L1 monotherapy improved the survival of mice with Brca1-null tumours, but not Brca2-null tumours." (PMID 38017453, 2023). "The third patient (case No. 4) carrying a BRCA1 and an FANCA mutation in the tumor had progressive disease after initiation of PARPi." (PMID 37173992, 2023). "We performed an observational study of all women diagnosed with non-mucinous high-grade EOC who underwent germline and tumour BRCA1/2 testing by the North West of England Genomic Laboratory Hub." (PMID 36765687, 2023). "PARP inhibitors are not an option for the treatment of these tumours characterised by BRCAness, since the activity of BRCA1 is fully restored." (PMID 37568604, 2023). "Where a germline PV or likely PV is not found, somatic testing of the tumour for BRCA1/2 is recommended." (PMID 36805919, 2023). "Comparison of tumorigenesis in these 88 mice with that in the control mice, which carry only mammary-specific Brca1 knockout by MMTV-Cre or WAP-Cre (Brca1-MSK n=118), indicating that the mice with Fgf pathway activation exhibited much faster tumor progression than the control mice." (PMID 37063417, 2023). "Exploiting this vulnerability, PARPi selectively target tumor cells lacking functional BRCA1 or BRCA2." (PMID 37958290, 2023). "Seven-hundred-two women diagnosed with non-mucinous high-grade EOC underwent germline and tumour BRCA1/2 testing." (PMID 36765687, 2023).